ALB (albumin)
Diseases named in the same sentence as ALB in open-access papers (continued):
Sharing a sentence is not in itself a finding about the gene and the disease.
diabetes (continued). "The two groups were similar regarding age, diabetes mellitus, C-reactive protein, diuresis and renal clearances, but serum albumin was significantly higher in included patients (p < 0.001)." (PMID 28859606, 2017). "On the other hand, blood Mn level was negatively correlated with diabetes mellitus (DM) (β = −1.453, p = 0.012) and serum albumin (β = −0.041, p = 0.935)." (PMID 29077007, 2017). "In conclusion, STZ-NA induced diabetes can lead to diabetic nephropathy by reducing plasma albumin level and enhancement of BUN, Cr and renal histopathology." (PMID 27921024, 2016). "The risk of infection increased with age and was higher in those with diabetes, in those prescribed a higher dosage of glucocorticoid, and in those with lower plasma albumin level." (PMID 27218256, 2016). "The markers examined included fasting glucose, insulin, adiponectin, and glycated albumin, as well as body mass index (BMI), use of medications, and history of diabetes." (PMID 27830830, 2016). "The clinical features of the false negative and the false positive subgroups were therefore compared; those with diabetes but who were falsely diagnosed had higher BMI, WC, and serum albumin concentrations." (PMID 26765575, 2016). "Baseline eGFR and the risk of CT-CIN showed a nonlinear relationship after adjustment for age, sex, BMI, history of diabetes mellitus, history of hypertension, serum albumin level, and the use of statins, ACE inhibitors, or ARBs." (PMID 27149474, 2016). "Older age and higher prevalence of diabetes were identified in the patients with lower albumin reach rates." (PMID 27542730, 2016). "The main statistically significant clinical variables associated with poor renal survival were lower Hb levels, higher sCr levels, lower serum albumin levels, comorbid diabetes mellitus, and previous diuretic use." (PMID 26779906, 2016). "The risk of infection increased with age and was higher in people with diabetes, in people given high glucocorticoid doses, and in people with low blood albumin levels." (PMID 27218256, 2016). "The level of B2-M in urine of the patients with diabetes was higher than normal and showed significant correlation with urinary albumin excretion and 2-hour postprandial blood sugar." (PMID 27293888, 2016). "The risks of infection increased with age and were higher in those with diabetes, in those prescribed higher glucocorticoid doses, and in those with lower plasma albumin level." (PMID 27218256, 2016). "In contrast, the albumin trend was upward sloped and the increment of albumin was remarkable in group B, despite the high prevalence of cardiovascular diseases and diabetes." (PMID 27015223, 2016). "The relationship between kidney function, HDL (r = −0.234, p < 0.001) and triglycerides (r = 0.151, p < 0.01) remained significant after adjustment for a history of hypertension, diabetes mellitus, smoking status and albumin concentration." (PMID 27005668, 2016). "Age, gender, BMI, duration of diabetes, chronic complications, HbA1c, lipid profile, creatinine, albumin, PA, RBP, and retinol were recorded." (PMID 28018921, 2016). "An increased urinary albumin excretion has been reported in the patients with hypertension or diabetes, as well as the individuals with a normal blood pressure." (PMID 27729008, 2016). "Serum glycated β-lipoprotein was disproportionately elevated compared to fructosamine and glycated albumin in diabetes patients with microvascular complications (group 3) and it correlated with rest of glycemic markers only in this group." (PMID 27896233, 2016). "Other factors associated significantly with SBP in univariable analysis were age, gender, diabetes, haemoglobin, haematocrit, albumin, cholesterol and calcium." (PMID 27071749, 2016). "Multivariate analysis revealed that responsiveness to LPD + EAA/KA was independently related to diabetes (p = 0.006) and high serum albumin levels (p = 0.011) in the LPD alone period." (PMID 27389019, 2016).
diabetes (continued). "They reported a significant positive correlation between PTH and OC and a positive correlation between OC and urine albumin excretion in diabetes patients." (PMID 27826545, 2016). "Diabetes increased blood glucose, urine albumin-to-creatinine ratio (ACR), kidney pathology and HDAC activity, and reduced renal E-cadherin levels." (PMID 27901066, 2016). "Serum albumin modifications have been reported in various diseases including types 1 and 2 of diabetes mellitus, renal failure, and end-stage renal disease." (PMID 27921024, 2016). "As expected, compared to the CAD−, the CAD+ patients had a lower hemoglobin and albumin level and a higher prevalence of concomitant diseases, including diabetes mellitus and hyperlipidemia." (PMID 27023477, 2016). "The greater impact of OVE diabetes on urine albumin compared to dextran suggested a more significant role for impaired tubule uptake." (PMID 27822483, 2016). "Other investigators have shown that retinal vessels can become leaky early during diabetes in the context of detection of serum albumin within the retina." (PMID 28119571, 2016). "Other co-factors such as older age, diabetes, low serum albumin and dialysis through temporary venous catheters are all independent risk factors for infection and sepsis." (PMID 27090094, 2016). "The objective of this study was to determine the activities of N-acetyl-β-D-glucosaminidase and alanine aminopeptidase and albumin concentration in urine samples of patients with type 2 diabetes mellitus." (PMID 27594733, 2016). "We examined the changes in glycated hemoglobin (HbA1c) and glycated albumin levels, the prescription frequencies, and the daily doses of each antidiabetic agent among patients treated regularly for diabetes during the 13-year study period." (PMID 27843494, 2016). "In general, more female patients received PD, fewer patients undergoing PD had diabetes, and those undergoing PD were younger, had lower hemoglobin and albumin levels, higher BMI, creatinine and fetuin A levels." (PMID 27398932, 2016). "About 30% of people with newly diagnosed type 2 diabetes mellitus have abnormally high urine albumin levels, and about 75% of them have microalbuminuria and 25% showed obvious diabetic nephropathy." (PMID 27921024, 2016). "Although urinary albumin excretion appears to reflect glomerular damage and subsequently renal tubulointerstitial damage, recently cases of diabetes have been reported in which renal function rapidly decreased without an increase in urinary albumin excretion." (PMID 27184495, 2016). "This randomized, double-blind, sham-controlled study enrolled patients with diabetes scheduled for elective PCI with eGFR ≤60 ml/min/1.73 m2 or urinary albumin creatinine ratio of >300 mg/g to receive either RIPC or the sham ischemic preconditioning." (PMID 27723839, 2016). "Univariate logistic regression analysis revealed that sex, diabetes mellitus, liver cirrhosis, baseline kidney function, total volume of radiocontrast agents, and serum albumin level were significantly different between the patients with and without CT-CIN." (PMID 27149474, 2016). "Patients in PO group were older, higher percentage of diabetes and faster peritoneal transporter, more co-morbidities, lower level of hemoglobin and serum albumin." (PMID 27093429, 2016). "P63cc completely prevented diabetes induction in 100% of the mice, while control bovine serum albumin-coupled cell-treated mice developed severe diabetes." (PMID 27292946, 2016). "There was a significant difference of the proportion of diabetes and β-blocker usage, and serum blood urea nitrogen, estimated glomerular filtration rate (eGFR), hemoglobin, albumin and total calcium levels among Ang-2 quartiles." (PMID 27991547, 2016). "Oral administration of RJ improves the serum levels of AST, ALT, ALP, TP, HDL-c, insulin, FBG and albumin in STZ-induced diabetes." (PMID 27602318, 2016).
diabetes (continued). "The renal function showed that an increase in serum urea, creatinine, uric acid, and urine albumin was disrupted by diabetes induction in the positive control group (G2)." (PMID 27525022, 2016). "Increased renal endothelin‐1 (ET‐1) production and an ETA receptor‐dependent increase in glomerular albumin permeability (Palb) accompany type 1 diabetes mellitus (T1D)." (PMID 28039404, 2016). "In obese subjects and patients with diabetes, with normal renal function, the synthesis of albumin and plasma concentration of albumin are unchanged from those of lean healthy controls, suggesting that the rate of degradation of albumin is also normal." (PMID 27338619, 2016). "The two groups did not significantly differ with regard to age, male-to-female ratio, duration of diabetes, body mass index, HbA1c, eGFR, or urinary albumin excretion levels at baseline." (PMID 27184495, 2016). "Glycated albumin levels, which reflect blood glucose levels over the previous two weeks and are useful in managing diabetes with chronic renal dysfunction." (PMID 27843494, 2016). "Genotypes were investigated in 39 patients with normal albumin excretion rate and duration of diabetes 13.46 ± 3.72 years and in 60 patients with microalbuminuria and duration of diabetes 15.28 ± 4.08 years (p = 0.11)." (PMID 27036319, 2016). "Symptoms of dyspnea, bilateral disease, diabetes mellitus (DM), immunosuppressive agent use, and low albumin levels, were the independent predictive factors for indeterminate QFT-GIT results in patients with culture-confirmed TB." (PMID 26070207, 2015). "Next, in the univariate analysis of technical survival among PD patients, age, albumin, 24-h urine volume, diabetes and peritonitis were used as correction parameters in the multivariate analysis." (PMID 26121574, 2015). "Several human studies have examined the effect of TZDs on urine albumin excretion in patients with diabetes mellitus." (PMID 26083376, 2015). "For example, enhanced glycation of albumin (major protein in circulation) with diabetes significantly impairs its normal antioxidant function, while at the same time it also acquires additional detrimental properties." (PMID 25878764, 2015). "Progression of CKD from stage 3 to 5 is predicted by male gender, diabetes, low hematocrit, high systolic B.P and low albumin." (PMID 26101512, 2015). "Instead, other studies have emphasized the importance of diminished albumin uptake by the tubules in governing albuminuria in diabetes." (PMID 26398934, 2015). "p- and R2-values of the correlations between %PB and renal function for pCG, HA, IAA, IS and pCS and the influence of added covariates total toxin concentration (CT), diabetes mellitus (DM) and albumin concentration in CKD patients." (PMID 26426048, 2015). "Patients who developed clinical outcomes during the follow-up period had higher prevalence of diabetes, lower platelets, higher bilirubin, lower albumin and higher glucose at baseline." (PMID 26083565, 2015). "There are many studies on urinary albumin (U-Alb) in diabetes and various other clinical conditions, but there is a notable lack of studies examining different ways of expressing albumin excretion in healthy individuals." (PMID 25616740, 2015). "To examine the downstream consequence of SIRT1 mediated alteration of ET-1 and TGF-β1 in diabetes, we investigated urinary micro-albumin levels to assess renal function in these mice." (PMID 25753689, 2015). "Patients with low iPTH levels (< 150 pg/mL) had low albumin and hematocrit levels, were older, and tended to have diabetes." (PMID 26107510, 2015). "Although the concentration of albumin in the proximal convoluted tubule in diabetes has been debated, we found that treatment of mPTCs with pathophysiologically relevant concentrations of albumin for 24 h induced these changes." (PMID 26398934, 2015).
diabetes (continued). "There are scant long-term trials looking at glycated albumin and chronic complications of diabetes, although one small long-term study found that glycated albumin correlated well with cardiovascular mortality." (PMID 26457201, 2015). "We recently reported that glycated albumin (GA) is increased in subjects with longer duration of diabetes and with decreased insulin secretory function." (PMID 26484352, 2015). "Urine analysis of the STZ induced diabetes rats showed also glucosuria and increased potassium, sodium, creatinine, uric acid, and albumin levels in the positive control group as a result of diabetic nephropathy, which is a major complication of diabetes." (PMID 25629046, 2015). "The CKD patients with diabetes had significantly lower serum albumin (P = 0.046) and lower serum magnesium (P = 0.023) and osteoporosis (P = 0.016) when compared to those CKD patients without diabetes." (PMID 26273297, 2015). "After adjustment for confounding baseline factors (age, gender, BMI, sagittal diameter, diabetes, hypertension, triglycerides and urinary albumin excretion), the hazard ratio was 0.37." (PMID 24798033, 2015). "Thirty seven urine samples from diabetes patients, with different levels of albumin-proteinuria were studied." (PMID 25874235, 2015). "In general, the patients receiving PD were younger, had a lower percentage of diabetes, lower albumin levels, and higher T-CHO and LDL-C levels." (PMID 25761189, 2015). "A multivariate logistic regression was performed using the statistically significant risk factors as identified by the univariate logistic regression, including age range, albumin, hemodialysis vintage, vascular access and diabetes status." (PMID 25780479, 2015). "Patients who reached the composite endpoint, were older, had a higher CRP, lower albumin and had more often a history of cardiovascular disease or diabetes." (PMID 25823004, 2015). "The following variables were retained in the final model: eGFR, serum albumin, calcium, Charlson Comorbidity Index excluding diabetes and renal disease (modified CCI), performance status (PS), and usage of erythropoiesis-stimulating agent (ESA)." (PMID 26057129, 2015). "The CKD patients with diabetes had lower serum albumin and a higher proportion of hypomagnesemia and osteoporosis than the nondiabetic patients did (P < 0.05)." (PMID 26273297, 2015). "A difference in the number needed to treat between subgroups defined by baseline factors was found when the SOS cohort was subdivided by median baseline urine albumin excretion (9.3 mg per 24 h), serum triglycerides (154 mg dl−1), diabetes and sex." (PMID 24798033, 2015). "The presence or absence of advanced hepatic fibrosis wasevaluated by NAFLD Fibrosis Score, a non-invasive method that uses age, BMI,AST/ALT ratio, albumin, platelet count and the presence or absence ofhyperglycemia or diabetes." (PMID 26734800, 2015). "The clinical features related to poor prognosis were: advanced age, past history of cerebral vascular disease and/or diabetes mellitus, decreased serum albumin level, higher CURB-65 or PORT index scores and QTc interval prolongation." (PMID 25705382, 2014). "In addition, we determined whether associations of UA and outcomes would be changed after controlling for uremic-related factors(albumin, hemoglobin, residual renal function, phosphate etc) and traditional CV risk factors (hypertension, hyperlipidemia, obesity, diabetes, etc)." (PMID 24416142, 2014). "Here we evaluated the effect of mPGES-1 deletion on diabetes-induced kidney injury via examining urinary albumin, the kidney weight and glomerular morphology." (PMID 24984018, 2014). "In order to examine the effects of hypertension superimposed upon diabetes on filtration barrier integrity, urine albumin-to-creatinine ratios (ACR; μg/mg) were determined." (PMID 25514595, 2014).
diabetes (continued). "At baseline, patients in the high BCL group were older and had a higher prevalence of diabetes mellitus but lower serum albumin, creatinine, and phosphate levels than the patients in the other 2 groups." (PMID 24428882, 2014). "Our study demonstrates that on multivariate Cox regression analysis, serum HS-CRP, albumin level, and diabetes all remain independent factors for predicting mortality and technique failure in PD patients." (PMID 24667814, 2014). "Patients with resistant hypertension had a higher incidence of diabetes, a remarkably higher level of serum sodium and albumin, and were more commonly prescribed with statins." (PMID 25490405, 2014). "In some studies glycated albumin is suggested as an alternative marker for glycemic control in many diabetes complications, including nephropathy, retinopathy and Alzheimer’s disease and also in the case of hemodialysis patients or gestational diabetes." (PMID 24708663, 2014). "Tamm-Horsfall protein appears to rise with increasing diabetes duration, whereas urine albumin excretion, a more conventional marker for the development of nephropathy, remains normal." (PMID 24667016, 2014). "The final prediction model contained seven predictors; age, smoking, history of macrovascular complications, duration of diabetes mellitus, Karnofsky scale, serum albumin and hemoglobin level." (PMID 24594735, 2014). "After 4 weeks of diabetes the urinary albumin to creatinine ratio (UACR) increased in both diabetic animals that subsequently received vehicle and in the animals that subsequently received the anti-β3 antibody compared with control nondiabetic rats." (PMID 25389530, 2014). "MG-H1 residue formation in albumin and other plasma proteins is increased in clinical diabetes and end stage renal disease." (PMID 24747646, 2014). "Several studies have demonstrated an association of this polymorphism with higher insulin sensitivity, a decreased risk of type 2 diabetes mellitus and its nephropathy and retinopathy, and a lower albumin excretion rate in patients with established diabetes." (PMID 24587794, 2014). "Serum albumin, γ-GTP, leptin, resistin, and hyaluronic acid, as well as the presence of diabetes, were associated with hepatic steatosis (≥5%) in the univariate analysis." (PMID 24524410, 2014). "Many studies have investigated the interaction between diabetes and inflammation, serum albumin and phosphorus, age and BMI, age and smoking status, as well as diabetes and BMI." (PMID 25329459, 2014). "The difference between the two diabetic groups is highly significant and indicates that the antibody inhibits the increase in excretion of albumin that occurs between 4 and 12 weeks of diabetes." (PMID 25389530, 2014). "A prolonged QTc interval was not related to serum calcium concentration and/or treatment with QTc prolongation drug, clarithromycin or azithromycin, but related to age, lower albumin concentration and past history of diabetes mellitus." (PMID 25705382, 2014). "The findings suggested that povidone-iodine should be used with caution and that special nursing care should be provided to patients with history of peritonitis or diabetes, inadequate dialysis, and low serum albumin level." (PMID 24997794, 2014). "The BSA aggregation was reviewed in terms of structural and biological impacts of glycation on the protein followed by reporting documents which indicate possibility of glycated albumin to be used as specific marker for diabetes." (PMID 24708663, 2014). "In diabetic mice, urinary albumin excretion (UAE) was ten-fold increased at an “early stage” of diabetes, and twenty-fold increased at a “later stage” (21 and 40 days, respectively after diabetes diagnosis) as compared to non-obese resistant controls." (PMID 24400109, 2014). "The preoperative variables included were as follows: age, sex, hypertension, diabetes mellitus, preoperative albumin and ALT levels, and MELD-Na score." (PMID 25342079, 2014).